MMP2 (matrix metallopeptidase 2)
Diseases named in the same sentence as MMP2 in open-access papers (continued):
Sharing a sentence is not in itself a finding about the gene and the disease.
colitis (continued). "DSS-induced colitis was found to be significantly attenuated in MMP-9-deficient mice, but not in MMP-2-deficient mice." (PMID 36289761, 2022). "Confirmation qPCR in the ipsilateral hippocampus demonstrated that acute colitis following craniotomy (Sham+DSS) resulted in a trend for increased expression of neuroinflammatory (Tspo, Cybb, Gfap, Psmb9) and neuropathology (Mmp2) genes compared to water-treated Sham mice." (PMID 33461596, 2021). "Here, we have shown novel MMP-2 and MMP-9 inhibitory activity from protein components of lupine, which were found to be active in vivo when administered orally, whilst alleviating the symptoms of induced colitis in mice." (PMID 34948082, 2021). "Minocycline was shown to reduced inflammation in DSS or TNBS models by reducing the expression of iNOS, proinflammatory cytokines, and MMP-2, -3, -9, and -13 with greater benefit seen in DSS induced colitis when it is combined with the probiotic E. coli Nissle 1917." (PMID 25948887, 2015). "Compared with the TNBS model group, the DAI scoring, plasma and colonic mucosa Hcy levels, MPO activity and contents of MDA, IL-1β, IL-6, TNF-α, MMP-2, MMP-9 in colon and EB in small intestine were significantly increased in the TNBS-induced colitis rats with simultaneous Hcy injection (P < 0.01)." (PMID 24787389, 2014). "Thus, MMP-9 rather than MMP-2 might play an important role in the pathogenesis of DSS-induced colitis via degradation of extracellular matrix proteins in ulcerative colitis." (PMID 36289761, 2022). "Heimesaat and colleagues demonstrated that MMP2 and MMP9 are involved in DSS-induced colitis but while MMP2 is crucial in the pathogenesis of colitis, MMP9 seems not to be essential." (PMID 25890182, 2015).
neuroblastoma (36 papers, 2002 to 2025). Neuroblastoma (NB) is the most common solid, extracranial childhood tumor. "Numerous studies have implicated that MMP-9 and MMP-2 are involved in invasive, metastatic, and poor prognosis of various cancers, including neuroblastoma." (PMID 30862004, 2019). "Increased MMP-2 expression in neuroblastoma has been associated with increased angiogenesis, advanced stage, and poor clinical outcome." (PMID 29221117, 2017). "Four studies investigated the expression of these enzymes in neuroblastoma, all of which indicated the expression of MMP-2 in neuroblastoma cell lines and tissue samples." (PMID 40426729, 2025). "MiR-338-3p was confirmed to suppress EMT pathway in neuroblastoma cells by targeting matrix metalloproteinase-2 (MMP-2)." (PMID 35628648, 2022). "Relative expression of miRNA-338-3p and MMP-2 in neuroblastoma tissues and GI-LI-N and SK-N-SH cells was determined by reverse transcription polymerase chain reaction experiment." (PMID 33817311, 2021). "This study aimed to explore the regulatory mechanisms of miR-338-3p and matrix metalloproteinase-2 (MMP-2) in neuroblastoma." (PMID 33817311, 2021). "Meanwhile, the suppression effects of miR-338-3p on cell proliferation and invasion in the two human neuroblastoma cells were partly reversed by MMP-2 overexpression." (PMID 33817311, 2021). "These combined findings indicated that miR-338-3p regulates the PI3K/AKT pathway in human neuroblastoma cells via MMP-2." (PMID 33817311, 2021). "For further investigating the molecular mechanism of miR-338-3p in human neuroblastoma cell invasion, the potential binding site between miR-338-3p and MMP-2 was predicted through the miRcode and miRbase online bioinformatics tools." (PMID 33817311, 2021). "In our research, we found that miR-338-3p decreased the ratio of p-PI3K/PI3K and p-AKT/AKT in human neuroblastoma cells, but this effect was reversed after MMP-2." (PMID 33817311, 2021). "In this study, the effects of miRNA-338-3p and MMP-2 on neuroblastoma cell growth and invasion were measured using in vitro techniques, and therefore these effects indeed need to be further confirmed by additional studies." (PMID 33817311, 2021). "Overall, the data of this study suggested that miR-338-3p indeed had an inhibitive effect on neuroblastoma cell growth, invasion, and EMT process through targeting MMP-2, which provided a new potential therapeutic target in the treatment of neuroblastoma." (PMID 33817311, 2021). "The results first time revealed the target relationship and regulatory mechanism between miRNA-338-3p and MMP-2 in neuroblastoma." (PMID 33817311, 2021). "Ribatti and co-workers studied neuroblastoma tumor samples using immunohistochemical staining to determine the expression of MMP-2 and MMP-9." (PMID 32751899, 2020). "In the more aggressive WAC-2 neuroblastoma line, MMP-2 expression was twice as high as that in the less aggressive 007 cells." (PMID 32751899, 2020). "N-Myc and Bcl-2 co-expression induces MMP-2 secretion and activation leading to tumorigenic phenotype in human neuroblastoma cells." (PMID 21876694, 2012). "Overall, those research findings confirmed the hypothesis that miR-338-3p could inhibit the cell invasion and EMT process in neuroblastoma by targeting MMP-2." (PMID 33817311, 2021). "We further surveyed whether miR-338-3p modulated the PI3K/AKT pathway through sponging MMP-2 in human neuroblastoma cells." (PMID 33817311, 2021). "Furthermore, miR-338-3p overexpression suppressed proliferation, invasion, and epithelial–mesenchymal transition (EMT) of neuroblastoma cells but promoted apoptosis, and the knockdown of MMP-2 triggered similar effects." (PMID 33817311, 2021). "MiR-338-3p sponged MMP-2 to regulate the PI3K/AKT pathway in human neuroblastoma cells." (PMID 33817311, 2021). "However, there was no study exploring the target relationship and regulatory mechanism between miR-338-3p and matrix metalloproteinase-2 (MMP-2) in neuroblastoma." (PMID 33817311, 2021).
neuroblastoma (continued). "Collectively, these data demonstrated that miR-338-3p could suppress cell growth, invasion, and EMT pathway and induce apoptosis in neuroblastoma cells by targeting MMP-2." (PMID 33817311, 2021). "BK treatment resulted in increased expression and activity of MMP-2 in neuroblastoma cells." (PMID 29867502, 2018). "Our main objective in this study was to evaluate the effectiveness of NM on neuroblastoma cells in vivo using the nude mouse xenograft model and in vitro, evaluating the effect of NM on cell viability, MMP-2 and -9 secretion, TIMP-2 secretion, Matrigel invasion and cellular apoptosis and morphology." (PMID 23446555, 2013). "Furthermore, miR-338-3p overexpression and the knockdown of MMP-2 could suppress the human neuroblastoma cell proliferation, invasion, and EMT pathway but promote the cell apoptosis." (PMID 33817311, 2021). "Importantly, this study also suggested that MMP-2 could rescue the inhibitive effect of miR-338-3p on neuroblastoma cell progression, cell invasion, and EMT process." (PMID 33817311, 2021). "Increased MMP-2 expression, in addition to decreased TIMP-2 expression, had a significant association with more advanced stages, and therefore, could possibly serve as a prognostic factor in patients with neuroblastoma." (PMID 32751899, 2020). "Our results indicate that chemerin may contribute to an increased MMP-2 synthesis in neuroblastoma." (PMID 29221117, 2017). "It has also been shown to inhibit MMP-2 and MMP-9 in SK-N-BE human neuroblastoma and HT1080 human fibrosarcoma cells." (PMID 38611849, 2024). "Subsequently, our study indicated that miR-338-3p indeed had an inhibitive effect on neuroblastoma cell growth, invasion, and EMT process through targeting MMP-2." (PMID 33817311, 2021). "Since MMP-9 is generally secreted in negligible quantities by neuroblastoma cell lines, including SH-SY5Y cells, it was possible to observe and quantify the effect of POE mainly only on the activity of MMP-2 secreted in the culture medium." (PMID 34677478, 2021). "Previously, primary esophageal squamous cancers were shown to express CMKLR1; neuroblastoma cells also express both receptors and there is evidence that chemerin acts via CMKLR1 in an α-NETA sensitive mechanism to increase MMP-2 to promote tumor growth." (PMID 30719206, 2019). "Chemerin induced calcium mobilization, increased MMP-2 synthesis as well as MAP-kinase- and Akt-mediated signaling in neuroblastoma cells." (PMID 29221117, 2017). "Advanced stages of neuroblastoma show increased expression of the matrix metalloproteinase (MMP-2), and a higher MMP-2 to TIMP-2 ratio has been shown to correlate with poorer prognosis for neuroblastoma patients." (PMID 23446555, 2013). "Previously, it has been reported that Bcl-2 promotes invasion and lung metastasis by inducing MMP-2 in NSCLC cells and coexpression of Bcl-2 and N-Myc induces MMP-2 secretion and activity in human neuroblastoma cells." (PMID 22748147, 2012). "PEGylated SN38 (EZN-2208), a novel topoisomerase I inhibitor, showed promising anti-neuroblastoma efficacy through increasing apoptosis and reducing expression of VEGF, MMP-2, and MMP-9 in preclinical in vitro and in vivo models of human neuroblastoma." (PMID 21876694, 2012). "On the other hand, MMP-2 and MMP-9 expression could be decreased in the presence of vitamin A. β-carotene can inhibit neuroblastoma cell invasion via different pathways (i.e., suppressing the expression and activity of MMP-2)." (PMID 38069361, 2023). "Therefore we can speculate that this effect of POE on the downregulation of pro-MMP-2 might reduce the in vivo invasiveness related to activation of pro-enzyme by activators present in the tumor microenvironment thus contributing to reduce the invasiveness of neuroblastoma." (PMID 34677478, 2021). "Our data illustrated that miR-338-3p could inhibit the neuroblastoma cell growth, invasion, EMT process, and PI3K/AKT pathway by targeting MMP-2." (PMID 33817311, 2021).
neuroblastoma (continued). "Furthermore, MMP-2 was directly targeted by miR-338-3p, and overexpression of MMP-2 rescued the inhibitory effects of miR-338-3p on human neuroblastoma cell progression." (PMID 33817311, 2021). "In human neuroblastoma cells, N-MYC and Bcl-2 co-expression induced MMP-2 secretion and activation." (PMID 30135355, 2018). "Similarly, BK induces the acquisition of the pro-metastatic phenotype of neuroblastoma cells, which is characterized by an increase in VEGF, the induction of MMP-2 expression, and the gelatinase activity of MMP-2 and MMP-9, keys for extracellular matrix degradation during invasion." (PMID 39519260, 2024). "Therefore, inhibition of MMP-2 and MMP-9 has great potential in the treatment of neuroblastoma." (PMID 30862004, 2019). "Increased expression of both MMP-2 and MMP-9 is also evident from studies in two neuroblastoma cell lines (LAN-5 and GL-LI-N) and immunohistochemical analysis of tissue biopsies of human neuroblastoma indicating that expression of these MMPs is correlated with angiogenesis in advanced stages." (PMID 21876694, 2012).
asthma (35 papers, 2009 to 2025). "The lack of MMP-2 reduced cellular infiltration and fibrosis in allotransplant models, whereas a deficiency in MMP-2 increased the susceptibility of mice to lethal asphyxiation in an asthma model." (PMID 37509076, 2023). "In fact, the absence of MMP-2 was protective in allotransplant models reducing cellular infiltration and fibrosis; in contrast, deficiency in MMP-2 increased the susceptibility of mice to lethal asphyxiation in an asthma model." (PMID 35625532, 2022). "In stable mild-to-moderate asthma, MMP-2 in association with MMP-3 is released from bronchial fibroblasts and may have a negative effect on lung function and AHR." (PMID 31547356, 2019). "While MMP‐2 and MMP‐9 are implicated in asthma, MMP‐9, MMP‐1, MMP‐13, MMP‐2, and MMP‐8 have been shown to be extensively involved in the progression of UC." (PMID 40568744, 2025). "Asthma-derived eosinophils also stimulated an increased expression of MMP2, MMP-9, MMP-12, TGF-β1 and TGF-β2 in MRC-5 fibroblasts also in correlation with an abnormal matrix turnover and airway fibrosis." (PMID 36911735, 2023). "It was shown that MMP-2 overexpression protects from asthma by promoting the polarization of macrophages to the M1 phenotype and reducing airway hyperresponsiveness and the expression of Th2 cytokines and IgE." (PMID 35456903, 2022). "Similar results were found in other asthma studies—the MMP-2 and MMP-9 levels were higher in asthmatic airways than in healthy ones." (PMID 35456903, 2022). "Our results observed the increased expression of MMP2 in asthma patients, which is consistent with that in previous literature." (PMID 34136532, 2021). "In the present study, the qualitative analysis of serum MMP-2 from equal number of subjects from three groups- controls, COPD and Asthma patients, revealed a significant elevation of serum MMP-2 in COPD patients and controls group [p < 0.0001; 95% CI]." (PMID 33198714, 2020). "Studies reported that the main function of Mmp2 protease is to degrade extracellular matrix proteins and participate in airway remodeling in asthma." (PMID 33133221, 2020). "MMP2 has beneficial effects in a mouse model of asthma, where this MMP facilitates the resolution of allergic inflammation by allowing cells to egress to the lung." (PMID 33020210, 2020). "We found significantly reduced plasma concentration of (total and active) MMP-2 in patients with asthma compared to a group of healthy volunteers." (PMID 31428095, 2019). "The level of the active form of MMP-2 in plasma as measured by zymography was also significantly decreased in patients with asthma compared to controls." (PMID 31428095, 2019). "Patients with asthma showed an increased gelatinolytic activity derived from MMP-2 and MMP-9 in their sputum." (PMID 27455234, 2016). "It has previously been shown that Mmp2 and Mmp9 are critically required by DC for recruitment to the airways in a murine model of asthma and for the migration of DC from the skin to lymph nodes." (PMID 19149869, 2009). "We speculate that the difference in serum MMP-2 in COPD vs Asthma can be exploited as a differentiating biomarker between Asthma and COPD, along with other respiratory diseases in a larger cohort." (PMID 33198714, 2020). "Notably, Mmp2 and Nr3c1 are two hub nodes, which are members of both component targets and asthma targets, making them crucial, accounting for PT in asthma treatment." (PMID 33133221, 2020). "In severe equine asthma, increased MMP-2 and MMP-9 levels were shown using gelatin zymography." (PMID 31316303, 2019). "Taken together, we presume that miR-29c expression induced by glucocorticoids might play important role in alleviating asthma through miR-29c targets such as MMP-2." (PMID 30075787, 2018). "Meanwhile, MMP-2 is one of main mediators in the pathogenesis of airway remodeling in asthma." (PMID 30075787, 2018). "Besides, animal experiments showed that PT could treat asthma by regulating the expression of Mmp2 and il-4." (PMID 33133221, 2020).
asthma (continued). "However, MMP-2-deficient mice have been reported to exhibit a reduced level of inflammation in their airspaces when compared with wild-type mice in an asthma model of lung disease, indicating a negative role for this MMP in pulmonary inflammation." (PMID 22911824, 2012). "Elevated levels of MMP-1, MMP-2, MMP-8, and MMP-9 have also been found in the sputum and bronchoalveolar lavage fluid of patients with asthma and COPD." (PMID 40940719, 2025). "They further demonstrated that TGF-β1 released from eosinophils further induced MMP-2, MMP7, MMP9 and MMP12 which are all essential for abnormal matrix turnover and myofibroblast differentiation in asthma fibrosis." (PMID 36911735, 2023). "Immunohistochemistry also showed that there was a marked increase in iNOS, MMP-2, MMP-9, and COX-2 in vehicle-treated asthma lungs." (PMID 36755351, 2023). "It is known that TIMP-1 binds and inactivates matrix metalloproteinases (MMP), specifically MMP-2 and MMP-9, with imbalances of the MMP-9/TIMP-1 interactions posited in the development of asthma." (PMID 34221020, 2021). "In bronchial epithelial cells, AhR agonists led to the upregulation of MMP2, MMP9, and MMP1 and proposed to contribute to airway remodeling in asthma and chronic obstructive pulmonary disease." (PMID 33488929, 2020). "In order to identify a distinct biomarker of COPD, serum neutrophil elastase (NE) and matrix metalloprotease-2 (MMP-2) from COPD and Asthma patients were compared; as these proteases tend to have overlapping activities in both the diseases." (PMID 33198714, 2020). "In unison with former studies, MMP-2/-9 and TIMP-1/-2 levels increased with severity of equine asthma and all MMPs/TIMP concentrations decreased with clinical score parameters within 2-6 weeks after CPG-ODN inhalation." (PMID 31316303, 2019). "Elastinolytic and collagenolytic activity was found in several studies on human asthma, in particular increased levels of MMP-9, but also MMP-2." (PMID 27938355, 2016). "Increased levels of MMP-1, MMP-2, and MMP-9 have been reported in the sputum and lung parenchyma of asthma or COPD patients." (PMID 23226927, 2012). "Furthermore, western blot analysis further confirmed that BIBF1000 treatment attenuated the lung expression of α-SMA, PCNA, iNOS, MMP-2, MMP-9, and COX-2, compared to vehicle-treated asthma lung tissues." (PMID 36755351, 2023). "MMP2 and MMP9 (gelatinases) are the most studied and well-characterized MMPs whose expressions and activations have been addressed in neoplastic pathologies and inflammatory disorders, including asthma." (PMID 37885469, 2023). "Moreover, MMP-2 and MMP-9 activities have been found to participate in the progression of asthma and especially shown to be involved in matrix remodeling and inflammation." (PMID 33374928, 2020). "The absence of lung tissue remodelling processes in Asthma as compared to COPD, also aligns well with our observation for nonsignificant difference in serum MMP-2 in controls and Asthma patients." (PMID 33198714, 2020). "Increased levels and activities of matrix metallopeptidase (MMP)-2 and MMP-9 have been observed in sputum or BALF from asthma patients compared to those from controls, and these increases were proportional to the severity of the airway inflammation and the extent of airway remodeling." (PMID 31086415, 2019). "Both MMP-2 and MMP-9 could promote the egress of inflammatory cells into airway lumen, an essential mechanism by which each MMP could exhibit a protective anti-inflammatory role in asthma." (PMID 27455234, 2016). "Interestingly, a distinct elevation of MMP-2 was observed only in COPD patients, but not in Asthma, as compared to controls." (PMID 33198714, 2020).
asthma (continued). "Hypoxia, which is associated with extracellular matrix remodeling in inflammatory lung diseases, such as fibrosis, COPD, and asthma, upregulated the expression of MMP-1, MMP-2, and MMP-9 precursors without subsequent activation in human lung fibroblasts and pulmonary vascular smooth muscle cells." (PMID 23226927, 2012). "Although no study reports the pathogenesis of miR-29c in asthma, a recent study demonstrated that miR-29c could regulates the expression of matrix metalloproteinase-2 (MMP-2) in primary rat aorta smooth muscle cells and MMP-2 is the target of miR-29c confirmed by luciferase reporter activity assay." (PMID 30075787, 2018).